ALK (ALK receptor tyrosine kinase)
Diseases named in the same sentence as ALK in open-access papers (continued):
Sharing a sentence is not in itself a finding about the gene and the disease.
lung cancer (continued). "Crizotinib, the ALK/MET TKI, has shown dramatic therapeutic effects against lung cancer with anaplastic lymphoma kinase (ALK) rearrangements." (PMID 27563816, 2016). "EML4-ALK-positive lung cancer is a primary malignant lung tumor consisting of cells that with a characteristic abnormal configuration of the DNA where the EML4 gene is fused to the anaplastic lymphoma kinase (ALK) gene." (PMID 27070423, 2016). "Lung cancer with ovarian metastasis or adnexal metastasis harboring anaplastic lymphoma kinase (ALK) gene translocation is rare." (PMID 27472693, 2016). "Crizotinib, the first clinically approved ALK inhibitor for the treatment of ALK-positive lung cancer has had less dramatic responses in neuroblastoma." (PMID 27049722, 2016). "Non-small cell lung cancer (NSCLC) is the most common type of lung cancer and anaplastic lymphoma kinase (ALK) gene rearrangement has been demonstrated to be associated with approximately 2–7% of NSCLCs." (PMID 27835601, 2016). "ALK rearrangement, MET amplification, BRAF mutation which account for 3–7%, 2–4%, and 1–3%, respectively, represent less frequent alterations in lung cancer." (PMID 27485414, 2016). "The recent discovery of driver mutations, such as epidermal growth factor receptor (EGFR) mutations and anaplastic lymphoma kinase (ALK) rearrangements, has dramatically changed the treatment of lung cancer." (PMID 27518729, 2016). "Molecular alterations in EGFR, KRAS, and ALK genes are involved in lung cancer pathogenesis, but clinical use of these biomarkers is still a debatable issue." (PMID 27863408, 2016). "Accurate detection of altered anaplastic lymphoma kinase (ALK) expression is critical for the selection of lung cancer patients eligible for ALK-targeted therapies." (PMID 27206799, 2016). "Previous studies identified three major genes (EGFR, KRAS, and ALK) for the development of lung cancer." (PMID 27863408, 2016). "Different assay approaches other than FISH have been proposed for identification of ALK rearrangement in lung carcinoma." (PMID 27769042, 2016). "The use of targeted therapies have led to an increase in survival of lung cancer patients with certain genetic alterations such as epidermal growth factor receptor (EGFR) activating mutations and anaplastic lymphoma kinase (ALK) rearrangements." (PMID 26603430, 2015). "Nearly 1% lung cancer harbored known ALK fusions, while in digestive tract cancer, the fusion rate was relatively low (0.15%, 1/662)." (PMID 26678488, 2015). "An apparent causal association between crizotinib treatment and renal cyst development emerged during clinical trials in anaplastic lymphoma kinase (ALK)-positive non–small cell lung cancer (NSCLC)." (PMID 25756473, 2015). "ALK gene amplification, mutation and rearrangement are known to be associated with tumor development in lung cancer patients; approximately 5% of NSCLC cases are diagnosed with ALK gene rearrangement." (PMID 27280107, 2015). "The discovery of an echinoderm microtubule-associated protein-like 4 (EML4)-anaplastic lymphoma kinase (ALK) fusion gene led to improved clinical outcomes in patients with lung cancer after the development of the first ALK-targeting agent, crizotinib." (PMID 25941796, 2015). "Similar efficacy was observed in EML4-ALK positive lung cancer patients treated with crizotinib and second-generation ALK inhibitors." (PMID 25789627, 2015). "Because anaplastic lymphoma kinase (ALK) is dependent on Hsp90 for protein stability, Hsp90 inhibitors are effective in controlling growth of lung cancer cells with ALK rearrangement." (PMID 26219569, 2015). "Recent advances added EGFR (Epidermal Growth Factor Receptor) and ALK (Anaplastic Lymphoma Kinase) as biomarkers that should be tested for in patients with advanced lung cancer." (PMID 25784483, 2015). "Anaplastic lymphoma kinase (ALK) rearrangements define a subgroup of lung cancer which is eligible to targeted kinase inhibition." (PMID 26678488, 2015).
lung cancer (continued). "Crizotinib, an ALK tyrosine kinase inhibitor, is currently approved to treat lung cancer patients exhibiting ALK gene rearrangements." (PMID 26312204, 2015). "Since ALK positive lung cancer patients are generally younger and fitter than the majority of lung cancer patients, low levels of testosterone can induce fatigue and reduced libido and impact on quality of life." (PMID 25955180, 2015). "Future studies should pay more attention to the ALK gene alterations in solid tumors in addition to lung cancer." (PMID 26678488, 2015). "This subset of lung cancer is addicted to high ALK activity for malignant growth, and in general it is dramatically sensitive to ALK-targeted agents such as crizotinib." (PMID 26370727, 2015). "The distinctive biomarkers in lung cancer are mutations in the epidermal growth factor receptor (EGFR) or gain-of-function translocations and inversions involving the anaplastic lymphoma receptor tyrosine kinase (ALK)." (PMID 26156018, 2015). "To conclude, in this study we report the frequency of EGFR mutations in a cohort of 956 lung cancer patients as well as the frequency of alterations in KRAS, BRAF, MET, PIK3CA and ALK genes in a subset of these patients." (PMID 26208325, 2015). "In lung cancer, copy number gain of ALK is a more frequent phenomenon than ALK rearrangement, and is reported in up to 63 % of cases." (PMID 26312204, 2015). "In our present study, we established three drug-resistant cell lines to investigate the mechanisms of acquired resistance to 17-DMAG in lung cancer with ALK rearrangement." (PMID 26219569, 2015). "A total of 487 lung cancer patients who underwent testing for ALK rearrangement in our department were included in this study." (PMID 26253541, 2015). "In recent studies, lung cancer patients with tumors harboring ROS1 or RET gene fusions have shown notable responses to ALK or other multi-target kinase inhibitors." (PMID 26124082, 2015). "It will provide new evidences to the potential role of ALK gene translocation in targeted therapy for other solid tumors, in addition to lung cancer." (PMID 26678488, 2015). "Currently, many detecting ALK expression assays are available or in development, clinical pathologists focus on how to choose the best method for routine diagnosis of lung cancer." (PMID 25676397, 2015). "Three hundred and forty-seven patients with locally advanced or metastatic ALK-positive lung cancers who had received one prior treatment, were given 250 mg oral crizotinib BID or intravenous chemotherapy with either pemetrexed or docetaxel every three weeks." (PMID 24955213, 2014). "More importantly, other ALK inhibitors were successively entered into clinical trials and promising to mark a new page of genotype-driven drug development for lung cancer." (PMID 24404167, 2014). "Some strategies have been proven effective in human trials, for example, the use of ceritinib, a new ALK (anaplastic lymphoma kinase gene) inhibitor, in patients with advanced lung cancers harboring genetic alterations in ALK, in a phase 1 study." (PMID 25147575, 2014). "Recently, Tanizaki and colleagues identified the EGF-mediated activation of HER family signaling as a mechanism driving such resistance by establishing lines of EML4-ALK–positive H3122 lung cancer cells resistant to the ALK inhibitor TAE684 (H3122/TR cells)." (PMID 23992330, 2014). "Crizotinib, as a novel ALK inhibitor, has been approved for advanced-stage ALK positive lung cancer by US FDA in August 2011, and by Chinese FDA in January 2013." (PMID 24667320, 2014). "These biomarkers predict response to these molecular targeting agents and testing for these markers is recommended in lung cancer patients, enabling personalized medicine for patients harboring EGFR mutations or ALK gene rearrangements." (PMID 24885886, 2014).
lung cancer (continued). "In several other tumor types besides lung cancer, ALK genomic alterations have been identified as potential oncogenic drivers, meaning that cancers in different organs can be targeted for treatment with ALK inhibitors regardless of their cell of origin." (PMID 25083769, 2014). "In the Lung1 cohort, when grouped by age, EGFR/KRAS/ALK alteration status, and smoking history, N39 further stratified lung cancer patients with significant differences in survival." (PMID 25146220, 2014). "ALK tyrosine kinase inhibitors (ALK-TKIs) have been proved to have good effects to ALK positive lung cancers." (PMID 24667260, 2014). "With the development of molecular subtype in lung cancer, NSCLC patients with EGFR-WT had been identified to carry several new “driver mutations”, including KRAS, HER2, and BRAF mutations, as well as ALK, ROS1, and RET gene fusion." (PMID 25277203, 2014). "Several clinical data have reported that administration of crizotinib, an inhibitor of ALK tyrosine kinases, was beneficial to lung cancer patients with ALK rearrangements." (PMID 24959902, 2014). "It becomes apparent that use of antibodies with high sensitivity and avidity to ALK will help find a pre-screening technique for fast, accurate, and cost-effective identification of patients with this subtype of lung cancer." (PMID 24667320, 2014). "Striking therapeutic advances in metastatic NSCLC have been observed with targeted agents using molecular selection, notable for patients with EGFR mutant or ALK-rearranged lung cancer." (PMID 25505733, 2014). "HSP90 inhibitors have shown activity in EGFR mutant lung cancer after the development of resistance, in ALK-rearranged tumors and more recently in EGFR wild type adenocarcinoma when combined with chemotherapy." (PMID 25505733, 2014). "IHC is a reliable detection method to screening the ALK in lung cancer, and then enhance the relevance ration." (PMID 24667260, 2014). "Our data are consistent with previously reported efficacy and safety findings and further support the use of crizotinib in patients with ALK-positive lung cancer." (PMID 25501361, 2014). "Crizotinib, an ATP-competitive aminopyridine inhibits tyrosine phosphorylation of ALK with an IC50 of 20-40 nM and response in 57% of patients with ALK-rearrangement positive lung cancer." (PMID 25364578, 2014). "ALK gene rearrangements are thought to be exclusive of EGFR and KRAS mutations and occur in approximately 4–7% of lung cancers." (PMID 25325013, 2014). "ALK-fusion lung cancer only overexpresses the 3′-ALK mRNA (NCIH3122 and NCIH2228), whereas sarcoma overexpresses the full-length mRNA." (PMID 24406431, 2014). "Ganetespib (STA-9090) is being tested in clinical trials for ALK-positive lung cancer patients, alone (NCT01562015) or in combination with crizotinib (NCT01579994)." (PMID 24722523, 2014). "Previous studies on a large, unselected population of adenocarcinoma with ALK rearrangement reported that patients with ALK-positive lung cancer were younger, female, and light or non-smokers." (PMID 24885886, 2014). "The fusion (rearrangement) of anaplastic lymphoma kinase (ALK) gene has been identified as an import factor to the tumorigenesis and development of lung cancer." (PMID 24667260, 2014). "But ALK protein is expressed at lower levels in lung cancer than in ACLC and IMT, and often can't be detected by conventional IHC." (PMID 24667320, 2014). "Due to the high world-wide lung cancer incidence (1.4 million deaths/year), ALK fusion positive lung cancers constitute the largest ALK positive patient population, comprising ~70,000 individuals." (PMID 24955213, 2014). "In the lung cancer literature, much attention has been devoted to the comparison of different ALK antibodies for immunohistochemistry." (PMID 25188507, 2014). "The small molecule inhibitor crizotinib has demonstrated high anti-tumoral activity, significantly higher response rate and longer PFS in ALK-positive defined lung cancers." (PMID 24423144, 2014).
lung cancer (continued). "Several driver mutations have been identified in lung cancer, such as epidermal growth factor receptor (EGFR) and K-ras mutations and anaplastic lymphoma kinase (ALK) rearrangement." (PMID 24885886, 2014). "One of the most intriguing recent discoveries in the field of lung cancer research is the identification of new driver mutations in lung adenocarcinomas, such as EGFR mutations and ALK fusion." (PMID 24926563, 2014). "Of the 36 patients with ALK-positive lung cancer, a mass and a nodule were identified in 17 (47.2%) and 16 (44.4%), respectively, indicating that more than 40% of advanced-stage ALK-positive tumors had a small-sized tumor." (PMID 24403104, 2014). "One case, which had characteristic histological patterns of ALK-positive lung carcinoma, was identified by IHC as possessing ALK expression, but FISH demonstrated that the carcinoma lacked ALK rearrangement." (PMID 25295103, 2014). "Based on recent publications, D5F3 appears to be a fairly popular choice for ascertainment of ALK protein expression status in lung carcinomas." (PMID 25188507, 2014). "As this component is known to be one of the characteristic histological findings in ALK-positive lung carcinoma, an awareness of marked mucin production is necessary to avoid an underestimation of the proportion of ALK-rearranged cells." (PMID 25295103, 2014). "Previous studies have revealed characteristic features, including adenocarcinoma histology and mucin production, in ALK-positive lung carcinoma." (PMID 25295103, 2014). "Previous studies have reported that IHC is a reliable screening tool for ALK-positive lung carcinoma." (PMID 25295103, 2014). "This proposition is in concert with the literature, which has shown in several different articles that immunohistochemistry can be very effective in the detection of ALK rearrangement in lung carcinomas." (PMID 25077070, 2014). "The present study evaluated immunohistochemistry (IHC) in ALK-positive lung carcinoma using two different antibodies, clone 5A4 and D5F3, and compared the results." (PMID 25295103, 2014). "To date, there have only been a few reports examining ALK rearrangement in lung cancer simultaneously by IHC, FISH, and RT-PCR, thereby allowing a direct comparison of these assays." (PMID 23936355, 2013). "ALK IHC testing in lung cancer remains challenging because of the relatively low expression of ALK protein, with many results showing this to be the case using ALK1 antibody." (PMID 23922677, 2013). "ALK is an RTK that has been associated with neuroblastoma and lung cancer, through different mechanisms." (PMID 24376513, 2013). "ALK inhibitors are now being developed as drugs; the TKI crizotinib is in use in lung cancer patients carrying the EML4-ALK fusion protein." (PMID 24376513, 2013). "In this study, we selected 192 lung cancer-related and miRNA genes for resequencing, although we only focused on the ALK fusions here." (PMID 23484153, 2013). "All 44 ALK-rearranged lung cancers were adenocarcinomas, with 2 cases having additional focal squamous components." (PMID 23922677, 2013). "Recently, the EML4/ALK fusion protein has also been demonstrated to trend toward positive prognostication in lung cancer." (PMID 23844053, 2013). "Although ALK-rearranged lung cancers make up only 5% to 7% of all NSCLC cases, they have demonstrated an impressive responsiveness to the ALK tyrosine kinase inhibitor, crizotinib, and represent a therapeutically important subcategory." (PMID 23922677, 2013). "Upon diagnosis of rearrangement of ALK gene in NSCLC lung cancers, drugs have been approved for clinical use." (PMID 23863689, 2013). "In the present study, immunohistochemical identification of ALK-positive lung cancer was performed according to a scoring system." (PMID 23936355, 2013).
lung cancer (continued). "Our immunostaining also confirmed intratumor heterogeneity of ALK rearrangement in primary tumors, and to our knowledge, this is the first report on ALK rearrangement in lung cancer at metastatic sites versus primary sites, which showed molecular differences." (PMID 23341890, 2013). "In previous reports, results of detailed clinicopathologic analyses of ALK-rearranged lung cancers have varied." (PMID 23922677, 2013). "Approximately 3–7% of non-small cell lung cancers harbor an anaplastic lymphoma kinase (ALK) gene fusion, constituting a new molecular subtype of lung cancer that responds to crizotinib, an ALK inhibitor." (PMID 23922677, 2013). "Histologically, solid, acinar, cribriform growth pattern with or without signet ring cell features have been reported to be the morphological characteristics of ALK-positive lung cancers." (PMID 23936355, 2013). "More recently, HGF was reported to induce resistance to ALK selective inhibitors in EML4-ALK lung cancer and BRAF inhibitors in BRAF mutant melanoma." (PMID 23690929, 2013). "These methods have different advantages and disadvantages and it remains to be determined which is the best method for large-scale screening of ALK rearrangement in lung cancer in a clinical setting." (PMID 23936355, 2013). "Crizotinib is a dual tyrosine kinase inhibitor of ALK and Met that shows potent anti-tumor activity, safety and feasibility as monotherapy in lung cancer patients with EML4-ALK rearrangements." (PMID 24386407, 2013). "One frequent characteristic of lung cancer is an aberration in which one or more receptor tyrosine kinases (RTKs), such as MET, EGFR, and ALK, are commonly overexpressed, amplified, or mutated." (PMID 23844053, 2013). "ALK-rearranged lung cancer can be identified by IHC, FISH, or RT-PCR with each method having advantages and disadvantages for screening." (PMID 23922677, 2013). "Despite the relatively low frequency of the EML4-ALK fusion, ALK-rearranged lung cancer is a unique molecular subgroup with a high sensitivity to ALK inhibitors, and is mutually exclusive from other well-known oncogenic mutations involving EGFR or KRAS." (PMID 23922677, 2013). "Although previous studies have evaluated ALK-rearranged lung cancers, the comprehensive analysis of lung cancer in Chinese has not well assessed." (PMID 23922677, 2013). "In our study, all 44 ALK-rearranged lung cancers were adenocarcinomas, with 2 cases having additional focal squamous components." (PMID 23922677, 2013). "We performed immunohistochemistry by using ALK antibody clone 5A4, the use of which has showed good sensitivity in ALK fusion detection in lung carcinomas." (PMID 23484153, 2013). "All these data confirmed the intratumor heterogeneity of ALK rearrangement in the primary lung carcinomas." (PMID 23341890, 2013). "Ganetespib (STA-9090) is also being utilized in clinical trials against ALK translocated lung cancer patients." (PMID 22363766, 2012). "Recent promising results of clinical trials with an ALK inhibitor, crizotinib, have changed the significance of ALK fusions in lung cancer, inflammatory myofibroblastic tumors (IMTs), and ALCL." (PMID 22347464, 2012). "In the present study, we developed a 5′-RACE method optimized for ALK fusion partner detection that was applicable to FFPE tissues and identified a novel fusion, kinesin light chain 1 (KLC1)-ALK, in lung cancer by using only an FFPE tissue." (PMID 22347464, 2012). "ALK rearrangement is gaining more importance and is included in the gene testing panel for lung cancer." (PMID 26316937, 2012). "This was based on the results of clinical trials for advanced lung cancers with ALK rearrangements, and early responses in ALK rearrangement assessed by FISH." (PMID 23342255, 2012). "We examined the impact of different predictive biomarker screening techniques and population enrichment criteria on the cost-effectiveness of targeted drugs in lung cancer, using ALK and crizotinib to build the initial model." (PMID 22374459, 2012).